DLK1 (delta like non-canonical Notch ligand 1)
Description:
May have a role in neuroendocrine differentiation.
Synonyms: DLK-1; FA1; DLK; pG2; Pref-1; ZOG; Delta1; PREF1
Tractability: Small molecule: a high-quality ligand is known; it belongs to a druggable protein family. Antibody: UniProt predicts a signal peptide or a membrane-spanning region. PROTAC: ubiquitination databases record sites on it; a small molecule that binds it is known.
Gene: Protein-coding gene on chromosome 14 (100,725,705 to 100,738,224, forward strand). Ensembl gene ENSG00000185559.
Subcellular location: Membrane; Cytoplasm
Subcellular location (Human Protein Atlas): Golgi apparatus
Pathways (Reactome):
Signal Transduction: Activated NOTCH1 Transmits Signal to the Nucleus
Gene Ontology:
Molecular function: protein binding; calcium ion binding
Biological process: negative regulation of Notch signaling pathway; negative regulation of ossification; negative regulation of osteoblast differentiation; positive regulation of bone resorption; positive regulation of osteoclast differentiation; regulation of bone remodeling; cell differentiation; negative regulation of cell differentiation
Cellular component: extracellular region; cytoplasm; membrane
Genetic constraint (gnomAD): Loss-of-function variants: 9 observed, 34.04 expected, observed/expected ratio (o/e) 0.26, 90% interval 0.16 to 0.46. The upper end of that interval is the gene's LOEUF score, 0.46, which puts it in group 2 of 6, group 1 being the genes least tolerant of losing a copy. Missense variants: 504 observed, 526.67 expected, observed/expected ratio (o/e) 0.96, 90% interval 0.89 to 1.03. Synonymous variants: 222 observed, 227.11 expected, observed/expected ratio (o/e) 0.98, 90% interval 0.88 to 1.09.
Homologues: Orthologues: chimpanzee DLK1 (99% identical), macaque DLK1 (93% identical), dog DLK1 (87% identical), rabbit DLK1 (86% identical), mouse Dlk1 (86% identical), rat Dlk1 (81% identical), pig DLK1 (81% identical), guinea pig DLK1 (76% identical), tropical clawed frog dlk1 (45% identical), Drosophila melanogaster NimA (21% identical). Paralogues in human: PEAR1 (31% identical).
Diseases named in the same sentence as DLK1 in open-access papers:
DLK1 is named in the same sentence as 192 diseases in open-access papers, as found by Europe PMC text mining. Sharing a sentence is not in itself a finding about the gene and the disease. The quoted sentences say what the papers report.
Obesity (56 papers, 2008 to 2025). Accumulation of substantial excess body fat. "DLK1 knockout mice exhibit skeletal malformations, increased adiposity, retarded growth with high perinatal mortality, and DLK1 mutations cause early onset puberty and obesity in humans." (PMID 40593645, 2025). "In humans, common allelic variants of the DLK1 gene have been associated with severe obesity in children (Trio families study) and circulating DLK1 is reported to be lower in obese individuals than in normal weight controls." (PMID 39468766, 2025). "In human, mutations in DLK1 gene have been reported as a cause of central precocious puberty associated with obesity and metabolic syndrome with undetectable DLK1 serum levels." (PMID 39702541, 2024). "For example, higher expression of the paternally expressed imprinted gene DIO3 is associated with diet-induced obesity in mice, and higher expression of the paternally expressed imprinted gene DLK1 is associated with higher levels of white fat in humans." (PMID 37928960, 2023). "DLK1 mutations have been reported as a cause of central precocious puberty associated with obesity and metabolic syndrome with undetectable DLK1 serum levels." (PMID 36568069, 2022). "Mice deficient in Dlk1 displayed growth retardation, obesity, skeletal malformations, and abnormalities of hematopoiesis." (PMID 23577002, 2013). "Dlk1 deletion in mice results in pre-natal and post-natal growth deficiency, mild obesity, facial abnormalities, and abnormal skeletal development, suggesting involvement of Dlk1 in perinatal survival, normal growth and homeostasis of fat deposition." (PMID 22563444, 2012). "Mutations in the Dlk1 gene result in precocious puberty and obesity; however, it is currently unknown if this phenotype is due to abnormalities in the functions of VMH DLK1 neurons, and if BDNF is somehow involved in the pathophysiology of the diseases." (PMID 41219904, 2025). "Previous studies have shown that Dlk1 knockout mice are highly susceptible to perinatal lethality, pre-and postnatal fetal growth restriction followed by metabolic disorders, and obesity after birth, indicating that Dlk1 plays a vital role in fetal growth promotion." (PMID 39543691, 2024). "Moreover, mutations in DLK1 gene have been reported as a cause of central precocious puberty associated with obesity and metabolic syndrome with undetectable DLK1 serum levels." (PMID 36568069, 2022). "It has been suggested that disruption of DNA methylation due to hyperglycemia might lead to abnormal placental DLK1 expression, causing metabolic disorders like obesity and insulin resistance to be passed on to future generations." (PMID 34540403, 2021). "Likewise, global, developmental deletion of DLK1 has been linked with obesity and anxio-depression." (PMID 33322758, 2020). "DLK1 prevents the differentiation of preadipocytes into mature adipocytes and thus Dlk1-null mice display obesity and growth retardation." (PMID 39468766, 2025). "In the present study, a decrease in the methylationindex of the DLK1 gene imprinting center was foundin one proband with PP, who also had obesity, pericallosallipoma, and hypogenesis of the corpus callosum." (PMID 40556973, 2025). "DLK1 pathogenic variants cause central precocious puberty (CPP) and obesity, suggesting that DLK1 links the well-established association between higher body mass index and earlier pubertal onset." (PMID 39468766, 2025). "According to animal studies, mice without paternally expressed DLK1 exhibit growth retardation and obesity while DLK1 overexpression generate decreased fat mass, diet-induced obesity resistance, and reduced insulin signalling." (PMID 39702541, 2024). "Mice overexpressing Dlk1 are resistant to HFD-induced obesity, whereas Dlk1 KO mice have accelerated adiposity." (PMID 37603466, 2023). "dKO mice were phenotypically similar to both Cd36-deficient and Dlk1 transgenic mice, namely in decreased amounts of WAT and resistance to HFD-induced obesity." (PMID 37603466, 2023).
Obesity (continued). "By understanding the correlation between the deletion of the DLK1 gene and an impaired lipid metabolism, researchers can gain valuable insights into potential therapeutic targets and strategies to combat obesity." (PMID 38203302, 2023). "Clinical studies have demonstrated that DLK1 protein concentrations in serum are associated with obesity and glucose intolerance, and serum DLK1 levels have been found to increase with obesity." (PMID 35063005, 2022). "Animal model studies have shown that DLK1 knockout mice exhibit growth retardation and obesity, while DLK1 overexpression leads to decreased fat mass, diet-induced obesity resistance and reduced insulin signalling." (PMID 36568069, 2022). "The aim of the present preliminary study is to investigate circulating levels of DLK1 within the context of human paediatric obesity and its relationship with clinical and biochemical parameters." (PMID 36568069, 2022). "Confirmation of this result on a larger population would allow to add circulating DLK1 level assessment as a new marker of metabolic alterations in adolescents with obesity." (PMID 36568069, 2022). "In conclusion, preliminary data obtained in the present study show lower DLK1 serum levels in subjects with obesity compared to lean controls." (PMID 36568069, 2022). "Our study reported lower serum levels of DLK1 in subjects with obesity suggesting its role in the regulation of adiposity even in the absence of syndromic condition or precocious puberty." (PMID 36568069, 2022). "Our previous in vivo studies demonstrated anti-adipogenic function of Dlk1 through findings that reduced fat in Dlk1 overexpressed mice and obesity phenotype in Dlk1 knockout mice." (PMID 34093239, 2021). "Here, we identified miR-379/miR-544 cluster as the critical regulator to resist HFD-induced obesity and regulate moderate hepatic steatosis via targeting Igf1r and Dlk1 directly." (PMID 34527673, 2021). "Although previous studies have indicated a relationship between DLK1 and diabetes and obesity, limited data specifying the link between the methylation status of DLK1 promoter and GDM development has been published." (PMID 31886292, 2019). "Obesity also results from deletion of paternally expressed genes, Peg3, Pref1/Dlk1, or Magel2 with observed differences in hyperphagia and energy expenditure, all of which demonstrate catch up growth in null mice." (PMID 30279096, 2018). "We also tried to replicate a SNP in exon 5 of DLK1 (rs1802710) because this SNP showed polar overdominance for obesity in children, but only a very slight trend (P = 0.32) was visible in our study." (PMID 25078964, 2014). "In the human syndrome of maternal uniparental disomy (matUPD14) where Dlk1/Pref-1 is silent, the patients exhibit a number of developmental abnormalities including obesity, hypotonia, premature puberty, macrocephaly, short stature, and small hands." (PMID 22844611, 2012). "A significant role of DLK1 in maintaining proper organism function was demonstrated by generating DLK1 knockout-mice, which exhibited accelerated obesity, growth disorders and skeletal malformation." (PMID 21637593, 2010). "Additionally, both approaches highlighted the association of DLK1 with obesity, but only DEGAS identified DLK1 association with T2D." (PMID 40982369, 2025). "Parent-of-origin effect (POE) is a phenomenon whereby an allele’s effect on a phenotype depends both on its allelic identity and parent from whom the allele is inherited, as exemplified by the polar overdominance in the ovine callypyge locus and the human obesity DLK1 locus." (PMID 40502026, 2025). "A SNP residing in DLK1 that showed paternal polar overdominance for human obesity is a maternal eQTL of MEG3, offering an explanation for the baseline risk of homozygous samples through association between MEG3 expression and obesity." (PMID 40502026, 2025).
Obesity (continued). "This discovery holds immense significance for comprehending the intricate role of the DLK1 gene in lipid metabolism and sheds light on the underlying mechanism that contribute to obesity without significant weight gain but with increased fat mass." (PMID 38203302, 2023). "Future studies focusing on the role of DLK1 in this process in humans would be warranted, as it could represent an interesting target for the treatment of obesity and its complications." (PMID 36568069, 2022). "In addition, a previous study revealed lower DLK1 serum concentrations in patients with obesity and Type 2 Diabetes (T2D) compared to non-T2D subjects." (PMID 36568069, 2022). "In this regard, DLK1 might play an important role in the pathophysiology of obesity and T2DM, which are common in the offspring of GDM mothers in the later stages of their life." (PMID 34540403, 2021). "However, the underlying molecular links among DLK1, IGF1/IGF1R signaling pathway, and miRNA-379/miR-544 cluster in obesity-mediated metabolic dysfunction, like NAFLD, are mostly poorly understood." (PMID 34527673, 2021). "Meanwhile, adult patients with DLK1 mutations present high frequency of metabolic alterations (overweight/obesity, early onset type 2 diabetes and hyperlipidemia), indicating that DLK1 may be a novel link between reproduction and metabolism." (PMID 31460623, 2019). "In addition, Pref1/Dlk1-null mice develop adult-onset obesity, while mice overexpressing Pref1/Dlk1 in adipose tissue develop a lean phenotype with glucose intolerance." (PMID 24416415, 2014). "Mice lacking paternally expressed Dlk1 display pre- and post-natal growth deficiency, obesity, facial abnormalities, and abnormal skeletal development." (PMID 22563444, 2012). "Furthermore, targeted deletion of Dlk1 in mice results in growth retardation, skeletal malformation and obesity and transgenic mice ectopically expressing ovine Dlk1 in some muscle fibres, exhibit muscle fibre hypertrophy." (PMID 18237417, 2008). "As DLK1 functions as a selective inhibitor of ACVR2B, it may have the potential to be adapted as a more targeted therapy for counteracting the loss of muscle associated with anti-obesity drugs, muscle wasting disorders, or cachexia." (PMID 40593645, 2025). "A remarkable finding, was the upregulation of the protein delta homolog 1 (DLK1), which is of great interest since it has been shown to inhibit adipogenesis and increase the expression of PPARs, thus proposed as therapeutic target for the treatment of obesity and diabetes." (PMID 35719139, 2022). "Interestingly, patients harboring DLK1 mutations showed more metabolic abnormalities, including glucose intolerance, type 2 diabetes mellitus, and obesity, than CPP patients not harboring DLK1 mutations." (PMID 35328752, 2022). "The dynamic expression of DLK1 and the controversies in literature findings can be explained by the heterogeneity of the individuals included in the several studies in terms of age, pubertal stage, gender, comorbidities (diabetes, obesity, cardiovascular diseases), or other variables." (PMID 36568069, 2022). "The Dlk1-Dio3 mat candidate NAFLD miRNAs may play some roles in obesity progression." (PMID 27135827, 2016). "Notably, Dlk1-null mice show growth retardation, accelerated obesity, and hyperlipidaemia." (PMID 22952470, 2012). "Our results showed that the DLK1 methylation was associated with 2 h OGTT glucose levels and birth weight, suggested that the epigenetic alteration around DLK1 could be one potential mechanism involved in fetal programming of obesity and other metabolic disorders in childhood and adulthood." (PMID 31886292, 2019). "Since TS14 is associated with absent expression of DLK1, which functions as a negative regulator for adipogenesis and plays an essential role in metabolic homeostasis, this may underlie the development of hypercholesterolemia and/or DM in the absence of obesity and hyperphagia in TS14." (PMID 39693239, 2025).
Obesity (continued). "In the present study has been observed a weak, albeit statistically significant, negative correlation between DLK1 serum levels and insulin-resistance degree in girls with obesity." (PMID 36568069, 2022). "Since we observed alterations in DLK1 DMR methylation and DLK1 expression in offspring after paternal exposure to CSE, DLK1 may provide an important clue to obesity induced by paternal exposure to cigarette smoke." (PMID 35063005, 2022). "The role of DLK1 in obesity is not completely clear but studies in animal models have shown that DLK1 may play a role not only in adipogenesis but also in adaptive thermogenesis in adipose tissue, the phenomenon also called browning." (PMID 36568069, 2022). "First, a murine Dlk1 knockout resulted in obesity but no reported effect on muscling." (PMID 22952470, 2012). "First, a murine DLK1 knockout resulted in obesity but no reported muscling phenotype." (PMID 20072617, 2010).
diabetes (20 papers, 2014 to 2026). "To support the DEGAS approach for identifying true markers of β-cell subpopulations or heterogeneity associated with diabetes, we selected DLK1 and CDKN1C as candidate genes for immunostaining in formalin-fixed paraffin-embedded (FFPE) human pancreas sections from ND and T2D donors." (PMID 40982369, 2025). "Expression of all miRNAs belonging to the Dlk1-Gtl2 locus was upregulated in diabetes-prone mice, while one of the most highly expressed miRNAs, miR-342-3p (a hub miRNA), was also increased in monozygotic twins with T2D." (PMID 41361331, 2025). "Among the altered miRNAs were imprinted miRNAs belonging to Dlk1-Gtl2 (22 miRNAs including miR-342-3p) and Mest (miR-335-5p) loci, which were upregulated and downregulated in diabetes-prone mice, respectively." (PMID 41361331, 2025). "Recent studies also implicate Dlk1 gene in the control of whole-body metabolism, the onset of diabetes in humans and mice, and adipocyte browning." (PMID 32899774, 2020). "We also showed that the human β-cell-specific gene DLK1 was significantly positively correlated with both MAFA and MAFB which had also been implicated in the progression of diabetes by impairing β-cell function." (PMID 30567413, 2018). "The loss of genomic imprinting (LOI) expression of DLK1-Dio3 miRNAs in acute promyelocytic leukemia (APL) and type 2 diabetes mellitus (T2DM) has been associated with altered DNA methylation at Gtl2 (MEG3)-DMR region." (PMID 27070142, 2016). "Using Metascape, we found that 4 genes (AZGP1, DLK1, GCKR and NEGR1) are linked to diabetes." (PMID 38184718, 2024). "Dlk1 gene is also involved in the development of obesity and diabetes." (PMID 32899774, 2020). "We found that the gene encoding Notch ligand delta-like 1 (DLK1) was downregulated by diabetes (p < 0.05 vs non-diabetic individuals), whereas the genes encoding delta-like 4 (DLK4) and jagged 1 (JAG1) remained unchanged." (PMID 31001672, 2019). "In a diabetes mouse model, CTNNB1 and DLK1 levels were further assessed using ELISA, Western blot, qRT-PCR, and immunohistochemistry." (PMID 41961207, 2026). "Signature genes included previously reported beta-specific genes like NKX6-1, DLK1, and ADCYAP1 (right) and alpha cell–specific genes like IRX2, LOXL4, and DPP4, a cell surface receptor and diabetes drug target." (PMID 27864352, 2017). "Another example for a strong influence of diabetes state on adipokine relationships is BMP7 and DLK1, which clustered differentially in obese patients with or without T2D." (PMID 24968098, 2014).